HRNR (hornerin)
Diseases named in the same sentence as HRNR in open-access papers (continued):
Sharing a sentence is not in itself a finding about the gene and the disease.
allergic disease (1 paper, 2022). An immune response that occurs following re-exposure to an innocuous antigen, and that requires the presence of existing antibodies against that antigen. "In the present study, both risk alleles HRNR rs877776[C] and FLG2 rs12568784[T] provided significantly increased risks for allergic sensitizations and the effects were independent of concomitant allergic diseases." (PMID 36013110, 2022).
Alzheimer disease (1 paper, 2025). A progressive, neurodegenerative disease characterized by loss of function and death of nerve cells in several areas of the brain leading to loss of cognitive function such as memory and language. "We identified four proteins (DSP, JUP, HRNR, and DDX6) that bind to amyloid‐beta (Aβ) oligomers derived from the brains of Alzheimer's disease (AD) patients." (PMID 40276647, 2025).
amyotrophic lateral sclerosis (1 paper, 2022). Amyotrophic lateral sclerosis (ALS) is a neurodegenerative disease characterized by progressive muscular paralysis reflecting degeneration of motor neurons in the primary motor cortex, corticospinal tracts, brainstem and spinal cord. "This means that this variant in HRNR occurs 1 in 300 Europeans, while other known pathogenic gene variants such as the Gly2019Ser variant of LRRK2 in PD (1 in 2,400 Europeans) or the Arg521Cys variant of FUS in amyotrophic lateral sclerosis (1 in 25,000 Europeans) are much less frequent." (PMID 35246273, 2022).
ductal carcinomas (1 paper, 2012). "It is possible that the enhanced fragmentation directly relates to the increase in intensity and abundance of hornerin detected in the lobular breast tissue tumor samples compared to the ductal carcinomas." (PMID 22727333, 2012).
folliculitis (1 paper, 2024). Inflammation of the hair follicles. "Folliculitis observed with tapinarof can be associated with increased follicular cornification with subsequent plugging, resulting from the upregulation of stratum corneum components, including filaggrin, hornerin, and involucrin." (PMID 39150292, 2024).
gout (1 paper, 2022). A condition characterized by painful swelling of the joints, which is caused by deposition of urate crystals. "As for the bioinformatic analysis of the highly expressed proteins in every group, the highly expressed proteins in gout including alpha-1-acid glycoprotein 1, desmocollin-1, and hornerin were significantly involved in “neutrophil degranulation”." (PMID 35359923, 2022).
HIV-1 infection (1 paper, 2025). The type species of lentivirus and the etiologic agent of acquired immunodeficiency syndrome (AIDS). "Therefore, RVBL1 and HRNR represent potential targets against HIV-1 infection and inflammation." (PMID 41226631, 2025).
ichthyosis (1 paper, 2021). Disorders of cornification that are characterized by visible scaling and/or hyperkeratosis of most or all of the skin. "After the genetic sequencing, variants were found in ABCA12 and HRNR which are related to several skin diseases, including ichthyosis." (PMID 34039366, 2021).
liver fibrosis (1 paper, 2023). "Indeed, being a component of the liver matrisome, it can be speculated that reduced levels of hornerin in both AIH and PBC patients may be correlated to the anomalous hyperplasia of connective tissue associated with liver fibrosis." (PMID 37569584, 2023).
osteosarcoma (1 paper, 2023). A usually aggressive malignant bone-forming mesenchymal neoplasm, predominantly affecting adolescents and young adults. "Hornerin-mediated multipolarity is not a cell type- or tissue-specific mechanism because similar centrosome perturbation by DDAs was observed in osteosarcoma epithelial cells, such as U2OS cells." (PMID 37596441, 2023).
pancreatic adenocarcinoma (1 paper, 2025). "Interestingly, Hornerin is highly expressed on endothelial cells in pancreatic adenocarcinoma in a VEGF-independent manner, and in vivo knockdown resulted in smaller vessels and reduced tumor growth." (PMID 40074836, 2025).
pancreatic cancer (1 paper, 2017). "Here, the authors interrogate the proteome of pancreatic cancer endothelium via phage display and identify hornerin as a critical protein whose expression is essential to maintain the pancreatic cancer vasculature through a VEGF-independent mechanism." (PMID 28916756, 2017).
pancreatic tumor (1 paper, 2017). "Hornerin had not been evaluated in endothelial cells prior to this study, and our identification of hornerin specifically on the endothelium adjacent to pancreatic tumor outgrowth directed us to investigate its function under conditions found in a growing tumor." (PMID 28916756, 2017).
renal carcinoma (1 paper, 2023). A carcinoma arising from the epithelium of the renal parenchyma or the renal pelvis. "Consistent with this, the mRNA expression level of hornerin showed the strongest correlation with the survival rate of patients with cervical, pancreatic, or renal cancer." (PMID 37596441, 2023).
renal cell carcinoma (1 paper, 2017). "Further exploration identified several other tumor types that express hornerin, including renal cell carcinoma (RCC) and prostate adenocarcinoma." (PMID 28916756, 2017).
sebaceous carcinoma (1 paper, 2025). "Hornerin is expressed by the ocular surface (corneal and conjunctival aspects, including meibomian and Zeis glands), the lacrimal apparatus and the skin, and has antimicrobial and protective (keratinisation) functions, reinforcing its potential role in sebaceous carcinoma." (PMID 41419736, 2025).
skin cancer (1 paper, 2020). "Furthermore, our analyses uncovered several recurring UV mutations following acute UVB radiation affecting multiple genes including HRNR, TRIOBP, KCNJ12, and KMT2C, which are frequently mutated in skin cancers, indicating their potential role as founding mutations in UV-induced skin tumorigenesis." (PMID 32188867, 2020).
spinal cord ependymoma (1 paper, 2025). An ependymoma that arises from the spinal cord. "Recurrent HRNR and FCGBP mutations observed in spinal cord ependymomas have also been reported in other tumor types." (PMID 41160379, 2025).
tumor (15 papers, 2012 to 2026). "Hornerin, part of the S100 protein family, has been linked to tumor progression in various entities." (PMID 40074836, 2025). "The high expression of HRNR in HCCs was significantly associated with vascular invasion, poor tumor differentiation, and advanced TNM stage." (PMID 30103712, 2018). "A functional role of hornerin was affirmed, as in vivo-specific knockdown of hornerin in tumor-associated endothelial cells resulted in decreased tumor burden along with alterations in vessel parameters as measured by vessel radius, vessel volume fraction, and fractal dimension." (PMID 28916756, 2017). "Furthermore, tumor weight was positively associated with the expression levels of HRNR." (PMID 30103712, 2018). "Nevertheless, SERPINB4 and HRNR appeared in the “Neoplasia of cells” list identified by the IPA software evaluation of gene pathways of interest." (PMID 35085295, 2022). "Our results demonstrated that HRNR promoted tumor progression and was connected with poor prognosis for HCC." (PMID 30103712, 2018). "Our results demonstrated that HRNR, which is frequently overexpressed in HCC, was linked with aggressive tumor phenotypes and poor prognosis for HCC patients after liver resection." (PMID 30103712, 2018). "We also found that inhibiting HRNR reduced tumour growth in the xenograft model with QGY-7703 tumour cells." (PMID 30103712, 2018). "We found that HRNR enhanced cell proliferation and colony formation as well as migration and invasion in vitro and tumor growth in vivo." (PMID 30103712, 2018). "We next determined the functional role of HRNR in aggressive growth properties of tumor cells by performing colony formation and migration assays." (PMID 30103712, 2018). "To explore the role of HRNR in HCC, we analyzed the expression of HRNR in tumor samples from a cohort of 271 HCC patients." (PMID 30103712, 2018). "Tumor vessels treated with Scr siRNA maintained high expression of hornerin, while hornerin expression in Hrnr siRNA-treated vessels was greatly reduced." (PMID 28916756, 2017). "Murine-specific hornerin knockdown in PDAC xenografts results in tumor vessels with decreased radii and tortuosity." (PMID 28916756, 2017). "The implication of hornerin in a VEGF-independent signaling cascade that modulates tumor vessel parameters prompts a need to discover the factors present in the L3.6pl secretome that were responsible for hornerin upregulation." (PMID 28916756, 2017). "Our results show decreased Gd-DTPA uptake and decreased Ktrans value in tumors treated with Hrnr siRNA, suggesting that hornerin knockdown results in both structural and functional vascular changes that lead to decreased tumor growth." (PMID 28916756, 2017). "As we were able to decrease tumor size, vessel parameters, and vessel function with targeted hornerin knockdown, we investigated if the combination of this approach with VEGFR inhibition would produce an enhanced therapeutic response." (PMID 28916756, 2017). "Notably, a discernible decrease in Hornerin expression was observed in MET + EAC, a protein of the S100 family associated with tumor progression in various entities." (PMID 40074836, 2025). "Collectively, the evidence suggests that HRNR, CRCT1, KPRP, and FLG2 promote cornification, which might underlie their potential tumor-suppressive action in relation to BC (see Discussion for details)." (PMID 37370814, 2023). "In addition to possessing tumor-suppression functions, these taxifolin-induced genes (HRNR, FLG2, CRCT1, and KPRP) reside in 1q21.3 and are coamplified in recurrent BCs with 1q21.3 amplification." (PMID 37370814, 2023). "There are, however, significant differences between PTMmut and overall mutations, with e.g., hornerin (HRNR, a paralog of FLG) being a top-10 PTMmut gene in 14/31 tumor types and versican (VCAN), collagen III (COL3A1) and XIV (COL14A1) all mutated in 9/31 tumor types." (PMID 33802493, 2021).
tumor (continued). "We further determined the role of HRNR in tumor growth in vivo by using xenograft HCC tumor models." (PMID 30103712, 2018). "HRNR promotes tumor progression and is correlated with a poor HCC prognosis." (PMID 30103712, 2018). "The expression levels of HRNR were assessed in tumor samples from a cohort of 271 HCC patients." (PMID 30103712, 2018). "Collectively, these data suggest that HRNR plays a critical role in HCC tumor growth in vivo." (PMID 30103712, 2018). "Knowledge of expression modulators could direct further studies into the signaling and mechanism of hornerin in tumor angiogenesis." (PMID 28916756, 2017). "Notably, we observed that the most dramatic effect of hornerin knockdown occurred at the later stages of tumor outgrowth (days 11–14)." (PMID 28916756, 2017). "Our data showing that hornerin alters tumor perfusion and blood oxygen saturation suggest that it may be involved mechanistically at several regulatory nodes that govern tumor oxygen status, a feature that is currently being investigated in our lab." (PMID 28916756, 2017). "Notably, treatment with Hrnr siRNA and AV-951 (combo) resulted in a 4.3-fold decrease in volume compared to the control group, indicating that inhibition of VEGF combined with hornerin knockdown results in an additive reduction in tumor growth." (PMID 28916756, 2017). "We next sought to determine if hornerin is expressed in human tumor specimens." (PMID 28916756, 2017). "To expand on this concept, we asked whether decreasing hornerin protein levels in combination with VEGFR2 inhibition would produce synergistic or additive reductions in tumor volume." (PMID 28916756, 2017). "While our study does reveal a critical role for endothelial cell-hornerin in regulating vessel parameters that are characteristic of the tumor vasculature, it does not address the function of hornerin in other cell types in the tumor microenvironment." (PMID 28916756, 2017). "We further evaluated hornerin regulation of tumor vasculature through photoacoustic microscopy (PAM), which permitted non-invasive analysis of critical vessel parameters such as blood flow rate, hemoglobin, and oxygen saturation in the same tumor over the course of treatment." (PMID 28916756, 2017). "We determined whether reducing HRNR expression ameliorated tumor growth." (PMID 30103712, 2018). "Finally, we explored the potential mechanism responsible for HRNR-mediated tumor growth." (PMID 30103712, 2018). "Notably, tumor growth was markedly inhibited by HRNR silencing in a xenograft model of HCC." (PMID 30103712, 2018). "Finally, hornerin knockdown combined with VEGF inhibition produced additive tumor volume and angiogenesis abatement, providing further evidence that compensatory pathways exist in tumor-associated endothelial cells." (PMID 28916756, 2017). "Elucidation of the factors, those that regulate hornerin and others that function downstream of hornerin, could have substantial clinical relevance by opening additional avenues of therapeutic intervention targeting the tumor vasculature." (PMID 28916756, 2017). "Previous studies have demonstrated that hornerin (HRNR)—a member of the S100 protein family—plays a role in regulating the mTOR signaling pathway and that it is a protein that promotes HCC tumor growth." (PMID 41169378, 2025). "Given that these BCs harbor 1q21.3 amplification and the increased copy numbers of HRNR, FLG2, CRCT1 and KPRP genes, these recurrent BCs are likely vulnerable to these genes-derived tumor suppressions." (PMID 37370814, 2023). "Hornerin (HRNR), a member of the fused-type S100 protein family, was shown to be expressed and to play a role in different tumor types." (PMID 35267445, 2022). "The heterogeneous expression of CD99, HRNR, and CANX in both healthy and tumor tissue hampered the quantitative comparison." (PMID 35267445, 2022). "To further explore the biological importance of HRNR in HCC, we examined the tumor growth in xenograft experiments." (PMID 30103712, 2018).
tumor (continued). "The proliferation assay showed that when HRNR expression was knocked down by HRNR-shRNAs in PLC/PRF/5 cells, tumor cells proliferation was suppressed compared with the PLC/PRF/5 scramble control cells (P < 0.01)." (PMID 30103712, 2018). "Each monotherapy, hornerin knockdown and VEGFR inhibition, produced a two-fold reduction in tumor volume." (PMID 28916756, 2017). "Conversely, genes related to epithelial differentiation and keratinization (FLG, FLG2, HRNR, TCHH, KRT73), immune regulation and tumor suppression (HLA-G, UNC5D), and metabolic signaling were downregulated, reflecting loss of tissue integrity and immune control." (PMID 41900972, 2026). "In addition, the knockdown of HRNR by shRNAs significantly inhibited the proliferation, colony formation, migration and invasion of HCC tumor cells." (PMID 30103712, 2018). "Moreover, the invasion assays demonstrated that knocking down HRNR significantly impaired the invasiveness of both PLC/PRF/5 and QGY-7703 tumor cells." (PMID 30103712, 2018). "After three rounds of in vivo phage screening, validation in vitro, and phage-based functional proteomics, we identified hornerin as a non-VEGF upregulated protein differentially expressed in tumor vessels." (PMID 28916756, 2017). "The cumulative data suggest that hornerin is not required to maintain the number of tumor vessels, however important vessel parameters such as VVF, tortuosity, pericyte recruitment, and radius are altered by the downregulation of hornerin expression." (PMID 28916756, 2017). "Preliminary evidence presented in this study suggests that hornerin knockdown does not alter accumulation of leukocytes in the tumor microenvironment." (PMID 28916756, 2017). "Our results indicate that neither hornerin knockdown nor VEGFR inhibition altered overall tumor proliferation in either of the three treatment groups compared to control." (PMID 28916756, 2017). "Further analysis of the tumor cellularity indicated that the proportion of leukocytes (CD45+CD31− cells) was not altered with hornerin knockdown, suggesting that immune cell infiltration into the tumor was not hornerin dependent." (PMID 28916756, 2017). "To provide further support for endothelial cell-hornerin knockdown and targeted siRNA specificity for murine and not human hornerin, we analyzed tumor sections for hornerin protein expression by immunofluorescent microscopy." (PMID 28916756, 2017). "To confirm hornerin knockdown in the tumor endothelium, we performed quantitative PCR (qPCR) on fluorescence-activated cell sorting (FACS) sorted tumor CD31+CD45− cells and observed a marked 78% reduction in hornerin transcript in the Hrnr siRNA-treated cohort." (PMID 28916756, 2017). "Normal pancreas endothelial cells (NPE) (arrows) were negative for hornerin expression, however tumor endothelial cells (TE) (arrows) near PDAC (arrowheads) stained positively." (PMID 28916756, 2017). "We also observed that hornerin expression increases in HUVECs in response to EGF stimulation, suggesting that one potential mechanism of elevated hornerin in the tumor endothelium is due to tumor cell-derived EGF, however these results remain to be explored in the tumor setting." (PMID 28916756, 2017). "As hornerin is present in tumor vessels but not normal vessels, we hypothesized that hornerin may play an important role in tumor vessel function and consequently regulate tumor progression." (PMID 28916756, 2017). "Compared to either untreated or non-targeting controls, cells lacking HRNR or CDCA8 showed significantly reduced proliferation; by contrast, the loss of KRT14 did not affect proliferation, suggesting that it was not required for tumour cell viability or growth." (PMID 31443478, 2019). "Immunohistochemical analysis of CD99, HRNR, and CANX confirmed the expression of these markers in the prostate but, due to high heterogeneity, with high- and low-expression areas in both healthy and tumor tissues, it was not possible to compare the two conditions." (PMID 35267445, 2022).